PYCR1 (pyrroline-5-carboxylate reductase 1)
Diseases named in the same sentence as PYCR1 in open-access papers (continued):
Sharing a sentence is not in itself a finding about the gene and the disease.
liver cancer (8 papers, 2022 to 2026). An epithelial or non-epithelial malignant neoplasm that arises from the liver. "PYCR1 has been reported to be associated with the insulin signalling pathway and to inhibit cell proliferation in liver cancer cells." (PMID 36088469, 2022). "Previous studies have shown that PYCR1 functions as an oncogene and promotes malignant progression in various tumors, such as lung and liver cancers." (PMID 40430095, 2025). "Schematic diagram illustrating the mechanism by which PYCR1 knockout/inhibition hinders liver cancer (LC) progression by regulating IRS1 expression through lactylation." (PMID 39422696, 2024). "The detailed function and potential mechanism of PYCR1 in liver cancer are still unclear to a great extent." (PMID 35293266, 2022). "Our goal is to determine the internal molecular mechanism of the interaction between SK and PYCR1 and its role in the occurrence and development of liver cancer." (PMID 35293266, 2022). "PYCR1, a key enzyme in mitochondrial proline biosynthesis, is upregulated in liver cancer in both humans and animal models." (PMID 36088469, 2022). "When the expression of PYCR1 was downregulated, it enhanced the inhibitory effect of SK on liver cancer cells." (PMID 35293266, 2022). "PYCR1 promotes the growth and metastasis of liver cancer cells by regulating IRS1 expression." (PMID 41458606, 2025). "indicates that the expression levels of PYCR1 and IRS1 may serve as potential diagnostic biomarkers for liver cancer." (PMID 41458606, 2025). "In addition, the knockdown of both P4HA2 and PYCR1 reduced cell proliferation of cervical and liver cancer cells, respectively." (PMID 35086476, 2022). "Because PYCR1 plays a cancer-promoting role in HCC, PYCR1 inactivation may become a molecular target for liver cancer therapeutic." (PMID 35293266, 2022). "However, SK and PYCR1 on autophagy and apoptosis of liver cancer cells are unclear." (PMID 35293266, 2022). "Thus, it is valuable to study the role of the PYCR1 gene in liver cancer." (PMID 35293266, 2022). "PYCR1 may is a new prognostic marker and a potential therapeutic target for liver cancer." (PMID 35293266, 2022). "Consistent with our recent findings in pediatric liver cancer, we also observed that CM272 markedly reduced the expression of amino acid metabolic enzymes (ASNS, PYCR1, BCAT2), as well as genes involved in the serine pathway (PHGDH, PSPH, PSAT1)." (PMID 39810240, 2025). "In summary, the detection of PYCR1, IRS1, Nucleolin lactylation, MADD, HDAC1, and HDAC2 holds potential clinical value in early diagnosis, prognosis assessment, and personalized treatment of liver cancer." (PMID 41458606, 2025).
renal cell carcinoma (7 papers, 2020 to 2024). "PYCR1 is highly expressed also in prostate cancer tissues, in renal cell carcinoma (RCC), in papillary renal cell carcinoma (PRCC) and in human malignant melanoma (MM)." (PMID 32500033, 2020). "We investigated the biological effects of overexpressing PYCR1 and PYCR2 in the human renal cell carcinoma Caki-1 and human embryonic kidney 293T cells in vitro." (PMID 39125668, 2024). "We knocked down PYCR1 and PYCR2 in the human renal cell carcinoma cell lines Caki-1 and A498 cells to investigate their biological functions in KIRC cells." (PMID 39125668, 2024).
colon cancer (5 papers, 2019 to 2023). "Western blot assays revealed that forced LINC01138 expression in colon cancer cells SW480 increased the expression of diacylglycerol kinase eta (DGKH) and Phosphodiesterase 4D (PDE4D), whereas resulted in decrease the expression of pyrroline‐5‐carboxylate reductase 1 (PYCR1) and transketolase (TKT)." (PMID 36366731, 2023).
kidney cancer (4 papers, 2022 to 2024). Primary or metastatic malignant neoplasm involving the kidney. "Subsequently, the authors applied diricore to kidney cancer and invasive breast carcinoma and discovered proline vulnerability and compensatory upregulation of Pyrroline-5-Carboxylate Reductase 1 (PYCR1), which catalyzes the last step in proline biosynthesis." (PMID 38273337, 2024). "Treatment with L-asparaginase induces proline metabolism dependency in kidney cancer, exhibiting high levels of PYCR1, a key enzyme in proline production." (PMID 35011702, 2022). "Suppression of PYCR1 attenuated kidney cancer cell growth when proline was restricted." (PMID 35011702, 2022).
multiple myeloma (4 papers, 2022 to 2025). "PYCR1 inhibition reduces myeloma cell proliferation and survival by triggering unfolded protein response pathway in vitro and in vivo to increase the efficacy of bortezomib." (PMID 39312378, 2024). "PYCR1 interference reduced myeloma cell proliferation and survival by inhibiting PRAS40-mediated protein synthesis." (PMID 35105345, 2022). "To identify the pathway of action through which PYCR1 inhibits myeloma growth, we performed a proteome profiling regarding phospho-kinases on OPM-2 cells." (PMID 35105345, 2022).
pancreatic cancer (4 papers, 2022 to 2025). "To further explore how FTH1 is linked to the reprogramming of proline metabolism in pancreatic cancer cells, we measured the protein expression of proline metabolism-associated molecules, PYCR1 and PRODH, in control and shFTH1-infected SUIT-2 cells through Western blotting." (PMID 39294443, 2024). "And the further analysis confirmed that the overexpression of PYCR1 may be associated with pancreatic cancer occurrence and progression." (PMID 35371311, 2022). "Taken together, these findings highlight the critical regulatory axis of FTH1 and PYCR1 in pancreatic cancer cell metabolism and survival, suggesting a shared pathway that influences malignancy and potential treatment targets in PDAC." (PMID 39294443, 2024). "We also observed that FTH1 and PYCR1 overexpression in SUIT-2/shFTH1#4 cells considerably rescued the inhibitory effects of 10 μM and 20 μM DFX after 72 h, suggesting that FTH1/PYCR1 expression is key for the anti–pancreatic cancer activity of DFX." (PMID 39294443, 2024). "Conversely, proline supplementation mitigated the effects of PYCR1 downregulation, partially rescuing the decrease in cell viability and suggesting a potential therapeutic strategy for counteracting the metabolic vulnerabilities of pancreatic cancer cells." (PMID 39294443, 2024). "Furthermore, expression analysis of miR-2355-5p and miR-5000-3p in pancreatic cancer patient samples from the TCGA database demonstrated an inverse correlation between miR-5000-3p and PYCR1 expression." (PMID 39294443, 2024). "The PYCR1 may serve as a potential therapeutic and prognostic biomarker for the treatment of pancreatic cancer." (PMID 35371311, 2022). "The expression level of PYCR1 was evaluated in pancreatic cancer." (PMID 35371311, 2022). "Collectively, these results suggest a complex regulatory network in which FTH1 influences pancreatic cancer progression by modulating PYCR1 expression, which in turn may be part of a feedback loop involving proline that controls the effects of FTH1, thus impacting cell viability and proliferation." (PMID 39294443, 2024). "However, more detailed studies are needed to confirm the mechanism of PYCR1 on pancreatic cancer." (PMID 35371311, 2022). "These stains show the effects of DFX on the tumor microenvironment, particularly regarding collagen deposition and the expression of FTH1 and PYCR1, which are key to understanding the mechanistic impact of DFX on pancreatic cancer cells and tissues." (PMID 39294443, 2024). "In this study, FTH1 expression was upregulated in most KRAS-mutant human pancreatic cancer cells and clinical pancreatic cancer tissues, contributing to PDAC progression through positive crosstalk with PYCR1 and promoting proline metabolism dysregulation." (PMID 39294443, 2024). "Our findings suggest that the interaction between FTH1 and PYCR1 leads to aberrant proline metabolism, subsequently inducing apoptosis in KRAS-mutant pancreatic cancer cells." (PMID 39294443, 2024). "In this study, we elucidated new mechanistic pathways highlighting the interplay between FTH1 and PYCR1, which appears to form a self-reinforcing loop that collectively drives the progression of KRAS-mutant pancreatic cancer." (PMID 39294443, 2024). "However, the effect and mechanism of PYCR1 in pancreatic cancer remain unknown." (PMID 35371311, 2022). "However, the expression and function of PYCR1 in pancreatic cancer remain unknown." (PMID 35371311, 2022). "Moreover, pancreatic cancer patients with low PRODH, P4HA and PYCR1 expression had longer survival times than cancer patients with higher expression; in contrast, patients with low PRODH2 expression had shorter survival times than those with high PRODH2 expression." (PMID 36088469, 2022).
papillary renal cell carcinoma (4 papers, 2019 to 2023). A rare subtype of renal cell carcinoma, arising from the renal tubular epithelium and showing a papillary growth pattern, which typically manifests with hematuria, flank pain, palpable abdominal mass or nonspecific symptoms, such as fatigue, weight loss or fever. "To determine PYCR1 expression level and confirm association between PYCR1 expression level and papillary renal cell carcinoma, we first analyzed the expression level of PYCR1 in PRCC tissues and corresponding tumor cell lines." (PMID 31428683, 2019). "And a study of papillary renal cell carcinoma demonstrated that phosphorylates Akt (p-Akt) and phosphorylates mTOR (p-mTOR) were inhibited by the suppression of PYCR1." (PMID 35371311, 2022). "We aimed to determine the function of pyrroline-5-carboxylate reductase 1 (PYCR1) on progression of papillary renal cell carcinoma (PRCC) and related mechanism." (PMID 31428683, 2019). "The result indicated that PYCR1 may regulate the progression of papillary renal cell carcinoma through the Akt/mTOR pathway 20,22." (PMID 35371311, 2022).
autosomal recessive cutis laxa (3 papers, 2017 to 2019). "Autosomal recessive cutis laxa (ARCL) results from a mutation in P5CR1 encoded by PYCR1." (PMID 28194412, 2017). "A study of pyrroline-5-carboxylate reductase 1 (PYCR1) deficiency, which causes a progeroid syndrome, may not only shed light on its genetic contribution to autosomal recessive cutis laxa (ARCL) but also help elucidate the functional mechanisms associated with aging." (PMID 30574417, 2018).
renal carcinoma (3 papers, 2020 to 2025). A carcinoma arising from the epithelium of the renal parenchyma or the renal pelvis. "Similarly, RNA-interference suppression of PYCR1 decreases levels of activated phospho-Akt and activated phospho-mTOR in renal cancer cells." (PMID 33083024, 2020). "We validated the expression of PYCR1 and PYCR2 in normal human kidney tissue and renal cancer cell lines Caki-1, 786-O, and A498." (PMID 39125668, 2024). "The expression levels of PYCR1 and PYCR2 in renal cancer cells were significantly higher than those in normal kidney tissue, consistent with the results of the previous analysis." (PMID 39125668, 2024). "In our experiments, silencing PYCR1 and PYCR2 in renal cancer cell line Caki-1 and A498 cells resulted in inhibited cell growth and migration, whereas overexpression of PYCR1 and PYCR2 promoted cell growth and migration." (PMID 39125668, 2024). "In vitro experiments demonstrated that PYCR1 and PYCR2 enhanced the proliferation and migration of renal carcinoma cells by activating the mTOR pathway, at least in part." (PMID 39125668, 2024). "Given the impact of PYCR1 and PYCR2 knockdown and overexpression on the biological functions of renal cancer cells, we further investigated the potential molecular mechanisms involved in KIRC." (PMID 39125668, 2024). "Varying proline concentrations showed similar effects, indicating that PYCR1 and PYCR2 activate mTOR via proline synthesis, influencing renal cancer cell proliferation and migration." (PMID 39125668, 2024). "Overall, these results suggest that overexpressing PYCR1 and PYCR2 in vitro can promote the growth and migration of renal cancer cells." (PMID 39125668, 2024). "In conclusion, these results indicate that inhibiting PYCR1 and PYCR2 in vitro can suppress the growth and migration of renal cancer cells." (PMID 39125668, 2024). "The biological functions and regulatory mechanisms of PYCR1 and PYCR2 were investigated by in vitro experiments in renal cancer cells." (PMID 39125668, 2024). "Considering PYCR1, PYCR2, and HF effects on the mTOR pathway, these findings suggest targeting proline metabolism, especially via HF-mediated inhibition, as a potential therapeutic approach for renal cancer." (PMID 39125668, 2024). "Finally, we explored the impact of PYCR1 and PYCR2 on cell growth and migration in renal cancer cells, revealing that PYCR1 and PYCR2 may exert their effects on renal cancer by activating the mTOR signaling pathway." (PMID 39125668, 2024).
allergic asthma (2 papers, 2022 to 2023). A asthma with a basis in a pathological type I hypersensitivity reaction. "Collectively, this study illuminates that proline and PYCR1 involved with airway remodeling in allergic asthma could be viable targets for asthma treatment." (PMID 37432745, 2023). "Similarly, proline and PYCR1 in lung tissues were high in a murine allergic asthma model induced by house dust mites (HDMs)." (PMID 37432745, 2023). "In addition, Pycr1 is vital for the development of HDM-induced allergic asthma in mice." (PMID 37432745, 2023).
bladder tumors (2 papers, 2021 to 2024). "Moreover, differential expression profiling in Cancer RNA-seq Nexus showed that PYCR1 is significantly increased in Grade 2, 3 and 4 but not Grade 1 bladder tumors in comparison to normal tissues, indicating its involvement in BLCA progression, invasion and metastasis." (PMID 33461172, 2021).
breast tumors (2 papers, 2018 to 2023). "PYCR1, overexpressed in breast tumors, is significantly associated with tumor growth, advanced grades and poor survival of patients." (PMID 37845207, 2023). "Functional genomics has confirmed that PYCR1 is required for malignant proliferation of breast tumors." (PMID 37845207, 2023). "We then measured cGMP levels and found that depletion of PYCR1 significantly reduced cGMP in both breast tumors and cancer cells." (PMID 37845207, 2023). "SLC1A5, GLS, PYCR1 and PIK3CA were significantly expressed in breast tumours with high expression of SLC7A5 (p < 0.001), while the low expression of SLC7A5 was associated with high levels of p-mTORC1 (p < 0.001)." (PMID 29566741, 2018).
cervical cancer (2 papers, 2019 to 2021). A primary or metastatic malignant neoplasm involving the cervix. "Furthermore, significantly elevated levels of the ETV4, PYCR1, and TTYH3 proteins were observed in HPV-negative cervical cancer tissues, but these proteins were rarely expressed in HPV-positive cervical cancer and normal cervical tissues." (PMID 33997099, 2021).
Insulin resistance (2 papers, 2019 to 2022). Increased resistance towards insulin, that is, diminished effectiveness of insulin in reducing blood glucose levels. "Transplantation of fecal microbiota from mice with co-exposure HFD and LDR with metabolic dysfunction resulted in increased disruption of metabolic dysfunction, insulin resistance and increased PYCR1 (Pyrroline-5-carboxylate reductase 1) expression." (PMID 36088469, 2022). "Herein, we observed that LDR strongly inhibited HFD-induced insulin resistance through PYCR1 activation to regulate insulin signalling, which is consistent with a previous report that inhibition of Akt/mTOR can induce insulin resistance." (PMID 36088469, 2022). "Our study gains a new insight into the potential prominent role of PYCR1 in regulating insulin resistance of HCC." (PMID 31619254, 2019). "This work further emphasizes the importance of the plasma metabolite PA and its interaction with innate insulin resistance within the context of the PYCR1 inhibition-mediated Akt/mTOR signalling involved in the manifestation of LDR + HFD-associated metabolic impairment." (PMID 36088469, 2022).
lymph node metastases (2 papers, 2022). "The univariate Cox regression revealed that poorer differentiation, regional lymph node metastases, and higher expression of PYCR1 were significant risk factors for overall survival (OS) in PDAC patients (P<0.05)." (PMID 35371311, 2022). "The results showed that the expression of PYCR1 in the lymph node metastasis group significantly increased (OR = 1.57, 95%CI: 1.06–2.33)." (PMID 36119513, 2022). "Our findings confirmed that PYCR1 expression was strongly correlated with clinical features (tumor TNM stage, lymph node metastasis, and distant metastasis stage)." (PMID 36119513, 2022). "We found that PYCR1 overexpression was significantly associated with higher cancer TNM stage, lymph node metastasis, and distant metastasis stage but not with cancer differentiation and cancer size." (PMID 36119513, 2022).
microcephaly (2 papers, 2017 to 2019). A congenital or acquired developmental disorder in which the circumference of the head is smaller than normal for the person's age and sex. "Moreover, the homolog of PYCR1, PYCR2, induces mutations related to microcephaly and hypomyelination." (PMID 31428683, 2019). "In another genetic disorder that is characterized by microcephaly and hypomyelination (the absence of lax and wrinkled skin), a mutation has been identified at residue Arg119 in PYCR2 which corresponds to the same mutated region in PYCR1 in affected individuals." (PMID 28194412, 2017).
neuroblastoma (2 papers, 2021 to 2023). Neuroblastoma (NB) is the most common solid, extracranial childhood tumor. "Many of these, e.g. NME1, PYCR1, TK1, BIRC5 and TOP2A, are located on Chr 17q, are upregulated in unfavorable neuroblastoma and associated with poor patient outcome." (PMID 37246217, 2023).
Obesity (2 papers, 2020 to 2022). Accumulation of substantial excess body fat. "Only six out of the 81 mitochondrial protein-encoding genes showed higher expression in the obesity-risk genotype (SEPT4, PYCR1, PRELID2, CPT1A, MTHFD1L, and FKBP10)." (PMID 32316277, 2020). "Mechanistically, increased PA levels in plasma can induce liver PYCR1 expression to further inhibit the IRS-1/Akt/mTOR signalling pathway and thus exacerbate HFD-induced obesity and metabolic dysfunction." (PMID 36088469, 2022).
Osteopenia (2 papers, 2018 to 2019). Osteopenia is a term to define bone density that is not normal but also not as low as osteoporosis. "Evidence has shown that patients carrying either homozygotic or heterozygotic mutations on the PYCR1 gene displayed typical premature aging symptoms of lax wrinkled skin, osteopenia, joint hyper laxity, and postnatal growth delay." (PMID 31091804, 2019).
prostate tumor (2 papers, 2007 to 2024). "Indeed, a role for PYCR1 in PCa was suggested by a 4-fold increased expression in human prostate tumors compared to adjacent normal tissue." (PMID 17553165, 2007).
pulmonary fibrosis (2 papers, 2020 to 2022). Chronic progressive interstitial lung disorder characterized by the replacement of the lung tissue by connective tissue, leading to progressive dyspnea, respiratory failure, or right heart failure. "PYCR1, a protein that indirectly fuels collagen production through proline metabolism, was also found to be upregulated and has recently been proposed as potential target for pulmonary fibrosis." (PMID 36531712, 2022). "This suggest that PYCR1 is the critical isoform in Pro biosynthesis during pulmonary fibrosis." (PMID 33093510, 2020).
airway hyperresponsiveness (1 paper, 2023). "Pycr1 deficiency restrained inflammation, airway hyperresponsiveness (AHR), and EMT, which may be associated with the regulation of mitochondrial damage, cellular metabolomic imbalance, and WNT3a/β-catenin and AKT/mTORC1 signaling activation." (PMID 37432745, 2023).